JUN (Jun proto-oncogene, AP-1 transcription factor subunit)
Diseases named in the same sentence as JUN in open-access papers (continued):
Sharing a sentence is not in itself a finding about the gene and the disease.
ocular hypertension (7 papers, 2013 to 2025). Abnormally high intraocular pressure. "It is possible DDIT3 and JUN act together, playing redundant and compensatory roles to integrate somal and axonal degeneration cascades in the context of ocular hypertension." (PMID 41397991, 2025). "The mitogen-activated protein kinase effector and transcription factor JUN was shown to be an important regulator of ocular hypertension-induced RGC somal apoptosis." (PMID 31632741, 2019). "Immunohistochemistry was performed to evaluate JUN expression in ocular hypertensive DBA/2J mice." (PMID 28726785, 2017). "Therefore, identifying the ocular hypertension-induced upstream regulator of both JUN and DDIT3 may be an important step in determining an upstream mechanism driving glaucomatous RGC death." (PMID 31632741, 2019). "DDIT3/JUN controlled the majority of RGC somal death in ocular hypertensive DBA/2 J mice but did not control axonal degeneration." (PMID 41397991, 2025). "JUN has both pro-death and pro-survival roles in RGCs after axonal injury to RGCs, making it possible that JUN-dependent pro-survival signaling is important for maintaining RGC viability after an ocular hypertensive injury." (PMID 28726785, 2017).
oral squamous cell carcinoma (7 papers, 2016 to 2025). "Metastatic oral cavity squamous cell carcinoma had 2.39-fold higher JUN gene expression than non-metastatic oral cavity squamous cell carcinoma (p = 0.025)." (PMID 30459815, 2018). "Metastatic oral cavity squamous cell carcinoma had 2.69-fold higher JUN gene expression than non-metastatic oral cavity squamous cell carcinoma (p = 0.012)." (PMID 30459815, 2018).
cocaine addiction (6 papers, 2019 to 2025). "CALM3 and JUN were downregulated in the cocaine addiction group compared to controls (p < 0.05), whereas CCL2, CD44, CLIC1, and VCAM1 were upregulated (p < 0.05)." (PMID 41465087, 2025). "Among up- and downregulated genes from the pathway hsa05030:cocaine addiction are genes JUN, GNAS, BDFN, and CDK5R1 (upregulated), and FOSB, NFKB1, CREB1 and PPP1R1B (downregulated)." (PMID 34947877, 2021). "JUN has been reported to be involved in amphetamine and cocaine addiction and their respective KEGG pathways." (PMID 30899073, 2019). "In summary, this study identified four key genes (FOS, IL6, EGR1, and JUN) that might be involved in cocaine addiction mechanisms and had potential roles as biomarkers and therapeutic targets for cocaine addiction." (PMID 37469839, 2023). "Moreover, they correlated these downregulated miRNAs to the upregulation of several networks associated with cocaine dependences comprehensive of PKC and JUN." (PMID 38069445, 2023). "JUN is also involved in the development of amphetamine and cocaine addiction." (PMID 30899073, 2019). "By broadening our perspective to incorporate the KEGG pathways, we also observed that ERBB2 (Hypo), NCK1 (Hypo), and JUN (Hyper) are members of the ErbB signaling pathway, while BDNF (Hyper) and JUN (Hyper) are constituents of the Cocaine addiction pathway." (PMID 40217422, 2025). "(Alcoholism, amphetamine addiction, cocaine addiction) ATF2, CREB1, CREB5, and FOSB in all three substance disease KEGG pathways are suspected be related with CREB and FOS family, and JUN." (PMID 30899073, 2019). "Seven nodes including JUN, FOS, RELA, MAPK1, ATF2, HRAS, and CREB1 in the backbone are the recorded genes of alcoholism, amphetamine addiction, or cocaine addiction in the KEGG pathways." (PMID 30899073, 2019). "Four key genes (JUN, FOS, EGR1, and IL6) were identified and well validated using CTD database correlation analysis, text mining, independent dataset analysis, and enrichment analysis methods, and they might serve as biomarkers of cocaine addiction." (PMID 37469839, 2023).
disc degeneration (6 papers, 2013 to 2025). "The observed ADAMTS 5 and inflammation-related gene expression (i.e. up-regulation of c-JUN, BIP, IL 1 and 8) in the current study are in accordance with these findings in the sense that they suggest mechanically induced disc degeneration." (PMID 23638074, 2013).
endometrial carcinoma (6 papers, 2016 to 2025). A malignant tumor arising from the epithelium that lines the cavity of the uterine body. "Herein, we demonstrated that knockdown of PGK1 inhibited the expression of c-JUN, FOSL1, and POLD1, indicating that PGK1 regulates chemoresistance in endometrial carcinoma through upregulation of DNA repair-related proteins." (PMID 30925862, 2019).
liver disease (6 papers, 2019 to 2025). "Comorbidities such as chronic inflammatory conditions or liver disease could influence the expression of genes like SERPING1 or JUN." (PMID 41137352, 2025). "In a previous study, researchers found that the transcription factor C/EBP Homologous Protein (CHOP) cooperates with c-JUN to upregulate SERPINA1, thereby exacerbating the burden of proteotoxicity, which plays a significant role in liver disease progression." (PMID 38710698, 2024).
renal fibrosis (6 papers, 2019 to 2025). A final common manifestation of a wide variety of chronic kidney diseases characterized by glomerulosclerosis and tubulointerstitial fibrosis. "In molecular docking assays, the hydroxy saffron yellow pigment A isomer also showed vigorous binding activity with AKT1 and JUN, indicating that it can intervene in the inflammatory pathway and has good potential to reduce the inflammatory response and thus ameliorate renal fibrosis." (PMID 41245191, 2025).
skin aging (6 papers, 2017 to 2025). The gradual irreversible changes in structure of skin that occur as a result of the passage of time.. "And JUN, TGF, and EGFR signaling pathways have been reported to influence blue-light-induced skin aging." (PMID 37626816, 2023).
adenoma (5 papers, 2008 to 2025). A neoplasm arising from the epithelium. "Phosphorylated FOS and JUN were exclusively detected in the adrenal cortex adjacent to functional adenomas (APAs and cortisol-producing adenomas), with negligible levels in cortex adjacent to non-functional adenomas and in normal adrenal cortex." (PMID 41412035, 2025). "The spatially restricted expression of phosphorylated FOS and JUN in the adrenal cortex adjacent to functional adenomas introduces a novel ancillary criterion, particularly valuable for lesions with equivocal hormone secretion profiles." (PMID 41412035, 2025). "Notably, FOS and JUN activation is restricted to the adrenal cortex adjacent to functional adenomas, highlighting a localized adaptive response to elevated ROS." (PMID 41412035, 2025). "Indeed, GSEA showed that loss of Mir34a in adenomas, and to a lesser extent in tumoroids, was associated with the induction of STAT3, JUN and SRF expression signatures." (PMID 36147476, 2022).
autism (5 papers, 2021 to 2024). Persistent deficits in social interaction and communication and interaction as well as a markedly restricted repertoire of activity and interest as well as repetitive patterns of behavior. "We then analyzed the association of JUN and PDGFRA with human ASD risk genes from the Simons Foundation Autism Research Initiative (SFARI) database by NetworkAnalyst." (PMID 35655651, 2022). "However, the transcriptional binding-factor motifs implicated in each condition implicated distinct biological mechanisms: neuronal JUN and FOS networks in autism vs. an inflammatory transcriptional network in dup15q microglia." (PMID 39079538, 2024). "JUN (DC = 19; BC = 3965), PDGFRA (DC = 40; BC = 3588), NTNG1 (DC = 47; BC = 4035) and GABRB1 (DC = 7; BC = 575) were associated with multiple neurodevelopmental disorders, including schizophrenia, bipolar disorder, Rett syndrome, seizures, and autistic disorder." (PMID 35655651, 2022). "We further explored the expression of JUN and PDGFRA in two relevant animal models of autism, the MIA and BTBR T+tf/J mouse models, which have been demonstrated to have increased Th17 cells and IL-17." (PMID 35655651, 2022).
dementia (5 papers, 2011 to 2024). Loss of intellectual abilities interfering with an individual's social and occupational functions. "Fluctuating ‘expression levels’ of other KRs—such as CTNNA3 and JUN—in various brain parts in of people with NDs hints at nature of their contribution in progression of dementia." (PMID 35327643, 2022).
head and neck cancer (5 papers, 2015 to 2023). A primary or metastatic malignant neoplasm affecting the head and neck. "The PI3K/Art pathway and the NF-κB pathway activation can initiate JUN expression in head and neck cancer." (PMID 32984316, 2020).
Hepatitis (5 papers, 2013 to 2024). Inflammation of the liver. "For example, c-JUN promotes hepatocyte survival in hepatitis and chemically induced stress models." (PMID 39684823, 2024).
Hodgkins lymphoma (5 papers, 2009 to 2023). A heterogeneous group of malignant lymphoid neoplasms of B-cell origin characterized histologically by the presence of Hodgkin and Reed-Sternberg (HRS) cells in the vast majority of cases. "Moreover, c-JUN and JUNB transcription factors reportedly promote the proliferation of classical Hodgkin’s lymphoma tumor cells through the transport of G proteins." (PMID 36978180, 2023).
invasive breast carcinoma (5 papers, 2014 to 2025). A carcinoma that infiltrates the breast parenchyma. "Moreover, c-JUN was reported to be associated with proliferation and angiogenesis in invasive breast cancer." (PMID 24466173, 2014). "High levels of c-JUN are detectable in invasive breast cancer cells as well as in aggressive breast tumors." (PMID 32365809, 2020). "However, COP1 was not the only molecule required to decrease c-JUN levels in invasive breast cancer cells, GSK-3β was also required to induce efficient c-JUN protein degradation." (PMID 32365809, 2020).
keratoconus (5 papers, 2020 to 2025). A degenerative, structural disorder of the eye, characterized by a cone-shaped protrusion of the cornea. "As a consequence, down-regulated voltage-gated calcium channels in CACNA1C, CACNA1G, CACNA1D1, and CACNA2D4, and purinergic receptors P2RX1 along with the down- regulated transcription factors including JUN and MYC can be attributed to reduced cell proliferation in keratoconus." (PMID 39420106, 2025). "The gene encoding cyclic AMP dependent transcription factor ATF3, decreased in both groups, regulates cell proliferation and differentiation, and is a stress response gene that interacts with JUN and FOS; additionally, related genes, JUND and FOLSL1 are both downregulated in the keratoconus samples." (PMID 32555404, 2020).
mesothelioma (5 papers, 2022 to 2024). A usually malignant and aggressive neoplasm of the mesothelium which is often associated with exposure to asbestos. "Among the Mesothelioma-specific hits we observed YREs in the loci of three MAPK-responsive TFs: JUN, FOSL1 and FOSB." (PMID 37400441, 2023). "We verified that in both cell lines MDM2 and JUN followed the same expression pattern previously observed in mesothelioma cells." (PMID 36672146, 2023). "In the JUN locus, we found one site upstream of its TSS (−361 Kb) highly enriched for H3K27ac and H3K4me1 histone enhancer marks and displaying mesothelioma-specific YAP occupancy, as well as binding by the AP-1 TFs FOSL1 and JUN itself." (PMID 37400441, 2023). "The nanoconstruct targeted EGFR (a mesothelioma overexpression receptor), and the main targets were genes involved in the progression of this cancer, e.g., BCL2, CDK1, and JUN." (PMID 35326459, 2022). "Additionally, the signal of H3K27ac, YAP1, JUN and FOSL1 was enriched in YREs specifically scoring in mesothelioma cells and not in common- or UM-specific hits." (PMID 37400441, 2023).
pneumonia (5 papers, 2006 to 2025). An acute, acute and chronic, or chronic inflammation focally or diffusely affecting the lung parenchyma, caused by an infection in one or both of the lungs (by bacteria, viruses, fungi, or mycoplasma.). "The analysis showed that 291 common and 14 hub genes were associated with pneumonia and that these genes could be regulated by the transcription factors JUN and NFκB1 carrying the NFκB binding site." (PMID 39205185, 2024).
basal cell carcinoma (4 papers, 2014 to 2021). A carcinoma involving the basal cells. "Moreover, in Basal Cell Carcinoma, YAP potentiates c-JUN mRNA and protein stability by sustaining c-JUN phosphorylation by JNK." (PMID 34782888, 2021).
cholestasis (4 papers, 2016 to 2023). Impairment of the bile flow caused by obstruction within the liver, or outside the liver in the bile duct system. "Cholestasis after ethinylestradiol is typically associated with ERa-JNK-c-JUN mediated upregulation of Mrp3 basolateral efflux transporter for BAs, which all were also reproduced in our study." (PMID 35388287, 2022). "Initially, the accumulated intrahepatic BAs during cholestasis activate the JNK signaling pathway to stimulate TNFRSF12A expression at the transcriptional level through increasing the binding activity of c-JUN to the TNFRSF12A promoter." (PMID 36690641, 2023).
Cirrhosis (4 papers, 2022 to 2025). A chronic disorder of the liver in which liver tissue becomes scarred and is partially replaced by regenerative nodules and fibrotic tissue resulting in loss of liver function. "Botanical drugs and gut microbiota target MAPK1, VEGFA, STAT3, AKT1, RELA, JUN, and ESR1 in the treatment of hepatitis B cirrhosis, and their combined use has shown promise for cirrhosis treatment." (PMID 38029250, 2023).
gout (4 papers, 2020 to 2023). A condition characterized by painful swelling of the joints, which is caused by deposition of urate crystals. "Activation of NFATc1, c-JUN, and TNF receptor-associated factor-6 (TRAF6) downstream of the RANK-RANKL signal pathway has also been regarded as a crucial step for formation in osteoclast-like cells in the pathogenic mechanism of gout." (PMID 36986544, 2023).
Hyperglycemia (4 papers, 2019 to 2025). An increased concentration of glucose in the blood. "JUN will be activated under long‐term hyperglycemia, promote the release of inflammatory factors, induce inflammation, enhance the expression of related apoptotic genes, and damage the function of islet cells." (PMID 41476996, 2025).
liver cirrhosis (4 papers, 2022 to 2025). "The focal adhesion pathway encompasses several genes, and KEGG analysis demonstrated that AKT1, CTNNB1, EGFR, FN1, JUN, and SRC were strongly related to curcumin compounds that might be influenced by liver cirrhosis in our study." (PMID 36297027, 2022). "Notably, HBV-miR-2 activated genes including inflammatory genes like P2RX7 and PYCARD, fibrosis-induced genes like ANXA2 and MIF oncogenic genes like FOS and JUN, which were further verified via RT-qPCR and highly expressed in the particular stages of CHB, liver cirrhosis and HCC." (PMID 40405227, 2025).
lung squamous cell carcinoma (4 papers, 1998 to 2025). "Pharmacological ubiquitin-specific protease 28 (USP28) inhibition reduces c-MYC, c-JUN, and Δp63 protein levels in mouse lung squamous cell carcinoma (LSCC) tumours and induces tumour cell death." (PMID 34636321, 2021). "MYC, JUN, and Δp63 are highly expressed in lung squamous cell carcinoma (LSCC) tumours." (PMID 34636321, 2021). "For this reason, immunohistochemistry was used to examine the squamous cell lung carcinomas from 121 patients for their expression of ERBB-1, vascular endothelial growth factor (VEGF), cyclin A, FOS, JUN and MYC." (PMID 9484827, 1998).
myocardial ischemia (4 papers, 2021 to 2025). A disorder of cardiac function caused by insufficient blood flow to the muscle tissue of the heart. "Studies have shown that JUN is closely related to the JAK2/STAT3 signaling pathway and the PI3K-Akt signaling pathway, and it can effectively treat acute renal injury caused by myocardial ischemia." (PMID 39339421, 2024).
neuropathies (4 papers, 2015 to 2021).
pancreatic ductal adenocarcinoma (4 papers, 2012 to 2023). An infiltrating adenocarcinoma that arises from the epithelial cells of the pancreas. "Transcriptome profile showed elevated TCF7, CTNNB1, and JUN expression in pancreatic ductal adenocarcinoma." (PMID 36457029, 2022). "Using NetRank, we identified seven genes (STAT3, FOS, JUN, SP1, CDX2, CEBPA, and BRCA1) as most relevant for predicting survival in patients with pancreatic ductal adenocarcinoma." (PMID 22615549, 2012).
acute myocardial infarction (3 papers, 2020 to 2025). Necrosis of the myocardium, as a result of interruption of the blood supply to the area. "JUN and the CXCL signaling axis represent potential targets for immunomodulatory therapy in acute myocardial infarction." (PMID 41291938, 2025). "They found that miR-146b overexpression significantly decreased the myocardial infarct size and cardiomyocytes apoptotic rates and release of creatine kinase and lactate dehydrogenase during IRI by targeting Smad4 and modulating the expression of c-fos and c-JUN in the myocardium." (PMID 33996940, 2021).
astrocytoma (3 papers, 2018 to 2022). "Infection of the astrocytoma cells with EEEV resulted in a significant upregulation of transcription factors ATF3, FOS, and JUN, with both ATF3 and JUN being at least partially transcriptionally dependent on EGR1." (PMID 35746681, 2022). "In fact, significant upregulations of MYD88, SRF, JUN, IL1B, TRIF, RIPK1, NLRP3 were detected in GBM cases compared to lower grade astrocytomas (AGII and AGIII)." (PMID 33446690, 2021). "Our transcriptomic data of U87MG cells 12 h after LPS stimulation and the TCGA RNASeq dataset of astrocytoma showed upregulation of genes related to inflammasome and ripoptosome pathways, namely MYD88, NLRP3, RIPK1 and RIPK3, and also SRF, JUN and IL1B, the downstream regulated genes." (PMID 33446690, 2021).
Atrophy (3 papers, 2008 to 2025). Any weakening or degeneration, especially through lack of use. "In this perspective, we think that our approach has given a good contribution: in fact we were able to identify some proteins and transcription factors, such as SMAD3/4, GNB2L1/RACK1, MYC, MAX and JUN whose functions have been studied extensively in tumours and in some atrophy models." (PMID 19108710, 2008).